IGF1R (insulin like growth factor 1 receptor)
Diseases named in the same sentence as IGF1R in open-access papers (continued):
Sharing a sentence is not in itself a finding about the gene and the disease.
breast cancer (continued). "IGF-1R has been shown to facilitate breast cancer survival, migration, invasion and metastasis." (PMID 21595894, 2011). "Moreover, it has been proved that IGF1R serves as an anchor for ESR1 in the plasma membrane of breast cancer cells." (PMID 21974810, 2011). "In multiple experimental systems including primary mammary tumors, cultured human cells, and Brca1-deficient mice, Shukla and colleagues showed that BRCA1 deficiency resulted in increased expression of IRS1, IGF1R and IGFBP2, and increased levels of serum IGF1." (PMID 19843326, 2009). "A role for IGF-1R in breast cancer metastases has been shown recently." (PMID 16457688, 2005). "IGF-1R signaling can therefore limit the antiproliferative effects of gefitinib in vitro, and we speculate that for a subset of human breast cancers, adding an anti-IGF-1R strategy to gefitinib treatment may be more effective than a single-agent approach." (PMID 15987464, 2005). "The role of IGF-1R in promoting the proliferation of breast cancer cells is well established." (PMID 16457688, 2005). "Interestingly, there was a pronounced increase in proliferation, migration, and adhesion due to the upregulation of IGF-1R-mediated signaling in the breast cancer cell line relative to the normal breast cell line, and this increase was reversed upon blocking IGF-1R." (PMID 39766058, 2024). "Phase I studies demonstrated that inhibiting the IGF-1R compensatory responses with mTOR inhibition could yield favorable clinical activity in advanced cancers, particularly in estrogen receptor (ER)-positive/high-proliferative breast carcinoma." (PMID 38584599, 2024). "However, clinical studies of IGF1R antagonism in breast cancer have been disappointing." (PMID 36920947, 2023). "Besides, high expressions of IGF-1R and Ki-67 may be the key factors for poor prognosis of breast cancer patients with diabetes mellitus." (PMID 35035440, 2022). "To determine IGF1R-mediated oncogenic roles of GASP1 in breast cancer cells, we ectopically expressed IGF1R in GASP1 knockout HCC1937 and MCF7 cells and found that GASP1 depletion suppressed cell proliferation compared with the control, while IGF1R overexpression could attenuate this effect." (PMID 36042202, 2022). "Although total expression levels of the IGF-1R are variable among breast cancers and do not show a consistent association with survival outcomes, IGF signaling pathway activity is elevated in most breast tumors, as would be anticipated with increased ligand production." (PMID 36556357, 2022). "The purpose of our study was to explore the effect of T2DM on the biological characteristics of breast cancer, and to investigate whether the difference of IGF-1R and Ki-67 expressions in breast cancer affects the prognosis of these patients with diabetes mellitus." (PMID 35035440, 2022). "Decreased IGF1R signalling might be expected to result in inhibition of cell line growth and/or promotion of apoptosis as this signalling system has been has been shown to promote breast cancer cell proliferation and survival." (PMID 35834073, 2022). "Furthermore, the results suggest that all these markers should be used in the earlier stages of the disease, since an analysis of BRCA patients indicated that the FGF2, FGFBP1, TGFA, TGFBR3, and IGF1R gene expression levels were present in late stages 3 and 4 of breast cancer." (PMID 36430763, 2022). "Besides, high expressions of IGF-1R and Ki-67 may be essential factors for poor prognosis of breast cancer patients with diabetes mellitus." (PMID 35035440, 2022). "Thus, we speculate that increased expression of GASP1 may decrease the response of breast cancer cells to paclitaxel by activating the IGF1/IGF1R-related pathways." (PMID 36042202, 2022).
breast cancer (continued). "Strong clinical associations between IGF-1R signaling and breast cancer risk and clinical outcomes, as well as extensive preclinical evidence implicating this pathway in multiple aspects of cancer progression, suggest a high therapeutic potential of targeting the IGF pathway in breast cancer." (PMID 36556357, 2022). "Moreover, overexpression of IGF-1R also decreases tumour latency time, increases the proliferative genetic signature and enhances migration potential in mammary tumours in addition to protecting cells against stresses of the tumour microenvironment and apoptosis." (PMID 34867402, 2021). "Taken together, standard radiation regimens may not be sufficient for AA patients with breast cancer due to the underlying molecular alterations in the IGF-1R signaling pathway." (PMID 35008602, 2021). "Thus, IGF1R was detected in association with the IGF1R promoter region in ER α-depleted, but not ER α-containing, breast cancer cells." (PMID 33918477, 2021). "However, the considerable overlap of functions between these receptors is exemplified in breast cancer where it has been suggested that inhibition of both IGF-1R and IR may be required for effective antitumour response." (PMID 33816477, 2021). "A number of factors may contribute to the failure of this strategy, including lack of IGF-1R expression in endocrine-resistant breast cancer and induction of hyperglycemia and hyperinsulinemia caused by IGF-1R mAbs2–4." (PMID 34611148, 2021). "This perhaps could be a reason why our result in females also showed an increased risk of melanoma by IGF1R rs2229765, although the result was nonsignificant, and its association with breast cancer is still inconclusive in the literature." (PMID 32150843, 2020). "Hence, lncRNA NR2F1‐AS1 induced IGF‐1 in breast cancer cells could activate the phosphorylation of IGF‐1R in HUVECs, which then took effects on angiogenesis." (PMID 32548873, 2020). "Hence, lncRNA NR2F1‐AS1 could promote breast cancer angiogenesis via IGF‐1/IGF‐1R/ERK pathway through sponging miRNA‐338‐3p." (PMID 32548873, 2020). "Thus, lncRNA NR2F1‐AS1 might promote breast cancer angiogenesis through activating IGF‐1/IGF‐1R/ERK pathway." (PMID 32548873, 2020). "HS6ST3 could promote breast cancer cell proliferation by upregulating IGF1R expression." (PMID 31921621, 2019). "Although the mechanism by which insulin B10 aspart increases the risk of breast cancer is not clear, many studies have proposed that this may be due to the high affinity of insulin B10 aspart for IGF-1R." (PMID 31555212, 2019). "Therefore, further understanding of the pattern of IGF1R expression in breast cancer and its potential impact on prognosis may be useful as these agents are being developed." (PMID 28766847, 2018). "Recent data showed that MET in combination with trastuzumab killed cancer stem cells and inactivated ErbB2/IGF-1R interactions in a synergistic manner via inhibiting Src kinase and/or PI3K/Akt pathway, causing overwhelming primary resistance to trastuzumab in HER2 positive breast cancer cells." (PMID 30483391, 2018). "In addition, we start by considering a cell state in which the source nodes IGF1R_T and PBX1 are ON (IGF1R is a common RTK in breast cancer signaling, and the subscript T denotes the intrinsic transcript level of IGF1R; PBX1 is a co-factor required for ER-dependent transcription)." (PMID 29623959, 2017). "Moreover, most recent clinical observations revealed that breast carcinoma patients with low IR expression levels had significantly longer progression-free survival and overall survival, while presence of phosphorylated INSR/IGF1R is related to poor survival in all breast cancer subtypes." (PMID 28038446, 2017). "While InsR did not provide any individual prognostic information regarding breast cancer events, there was a significant effect modification of InsR on the association between the combined IGF1R and pIGF1R/InsR markers and event-free survival (Pinteraction = 0.041)." (PMID 28030849, 2017).
breast cancer (continued). "Considering that IGF1R deregulation is not limited to ErbB2+ breast cancer, our data widen the scope of breast cancer subtypes that may respond to phenformin treatment to include ErbB2-negative breast cancer with IGF1R deregulation, yet further investigation is necessary." (PMID 28947975, 2017). "Furthermore, since IGF1R is an established oncogenic factor in breast cancer and has been the focus of numerous clinical trials, it is potentially of therapeutic importance that we have shown that co-targeting both IGF1R and SphK1 in vitro has a synergistic benefit." (PMID 29207959, 2017). "Moreover, our preclinical findings suggest that co-targeting IGF1R and SphK1 may have benefit in some women with breast cancer and requires further investigation." (PMID 29207959, 2017). "Moreover, IGF1R expression is reported to be significantly associated to HER2-positivity and poorer disease-free survival in premenopausal women, suggesting a link between IGF1R and HER2 specifically in pre-menopausal breast cancer." (PMID 29207959, 2017). "Similarly, the IGFBP3, IGF1R, IRS1, and PI3KCB genes have a purported relationship with breast cancer risk due to either their role in IGF1 signaling regulation, or association with strong breast cancer risk factors." (PMID 27376028, 2016). "Direct links between activated IGF-1R signaling and the acquisition of stem cell- and EMT-associated properties were recently reported in the CICs of several tumors, including lung adenocarcinoma, hepatocellular carcinoma, colon carcinoma, glioma and breast cancer." (PMID 27764776, 2016). "While we studied the effect of insulin analogues on MG tumor development, we cannot exclude that insulin analogues with high affinity for the IGF1R may also promote breast cancer progression, either locally or at distant sites, or modulate sensitivity to anticancer drugs." (PMID 25848982, 2015). "Nonetheless, tamoxifen-resistant (TamR) breast-cancer cells may exhibit reduced levels of IGF-1R." (PMID 25798130, 2015). "IGF1R expression retained a significant and independent prognostic value for OS by multivariate analysis, as well as the age of the dog at neutering, occurrence of a new primary mammary tumor, histological grade, surgical margin status and presence of central necrosis." (PMID 26449867, 2015). "Accordingly, inhibiting IGF-1R signaling may be a new strategy for the treatment of breast cancer." (PMID 24618835, 2014). "Expression of IGF-1R has been shown to correlate with an unfavorable prognosis in several types of cancer, e.g. in advanced oral squamous cell carcinoma, but also with a favorable prognosis in studies in breast cancer, non small cell lung cancer and soft tissue sarcoma." (PMID 24489919, 2014). "Also several genes and SNPs with significant associations with breast cancer risk have been observed yet associations with SNPs of IGF1R have not been elucidated." (PMID 24392142, 2014). "In addition, IGF-1R antibodies and small molecule inhibitors have been investigated as therapy for other malignancies, including breast cancer, colorectal cancer, non-small cell lung cancer, ovarian cancer, pancreatic cancer, prostate cancer, leukemia, and rhabdomyosarcoma." (PMID 24349301, 2013). "To better understand the molecular mechanisms that regulate LIP expression in metastatic breast cancer, we set out to determine in mammary epithelial cells whether IGF-1R signaling leads to an increase in LIP expression and whether LIP plays a role in IGF-1R mediated suppression of anoikis." (PMID 21854628, 2011). "While our model system involves increased IGF-1R activity due to receptor overexpression, it must be noted that increased IGF-1R signaling in clinical breast cancer might also arise from mechanisms involving abnormally high IGF-2 expression or from derangements in IGF-binding protein physiology." (PMID 15987464, 2005).
breast cancer (continued). "In human breast cancer patients, expression levels of KRT14 and KRT6A negatively correlated with expression of IGF1R." (PMID 42279332, 2026). "In breast cancer, macrophage-derived CXCL1 activates an IGF1R/STAT3/HMGB1 axis that promotes autophagy-mediated paclitaxel resistance and inhibits apoptosis." (PMID 41465435, 2025). "Others have shown that this phenolic compound can mimic the effects of anti-oestrogens by altering key growth regulatory signals involving ER/cyclin D1 and IGF1R/p-AKT, thereby reducing the proliferation of breast cancer cells." (PMID 40493253, 2025). "In breast cancer, GDF15 overexpression drives the epithelial-mesenchymal transition (EMT) phenotype through the IGF-1R-FoxM1 signaling pathway." (PMID 40144214, 2025). "In this study, Yang and colleagues also demonstrated that silencing CXCL1 or blocking IGF1R/STAT3 signaling disrupts this HMGB1–autophagy–MRPs axis and restores drug sensitivity in breast cancer." (PMID 41465435, 2025). "Collectively, our research highlights the important role of TAMs/CXCL1 in mediating breast cancer chemoresistance through the regulation of autophagy, and proposes IGF1/IGF1R as a potential upstream signaling that governs autophagy via STAT3/HMGB1 activation." (PMID 39394189, 2024). "In breast cancer, the IGF1/IGF1R axis triggers STAT3-dependent transcriptional activation of S100A7, a cytokine-like molecule binding to RAGE." (PMID 38892104, 2024). "Taken together, these data indicate that ITGB1 expression distinctly alters IGF-1R location in less migratory, hormone-responsive MCF-7 cells compared to more aggressive TNBC Hs578T breast cancer cells." (PMID 39608716, 2024). "Keywords utilized in the search encompassed “Insulin-like Growth Factor-1 (IGF-1)”, “IGF-1 receptor (IGF-1R)”, “IGF-1 isoforms”, “breast cancer”, “tumorigenesis”, “apoptosis inhibition”, “signal transduction”, “cancer metastasis” and “therapeutic targets”." (PMID 39273251, 2024). "Breast cancer tissues in TMA were utilized to investigate the clinical significance of CXCL1 and its relevance with HMGB1, IGF1R, and CD163 expressions." (PMID 39394189, 2024). "The IR-to-IGF1R ratio was generally higher in hepatic and AML cells, while breast cancer cells showed varying but lower ratios given higher IGF1R expression levels." (PMID 39572596, 2024). "Quantum dots were also conjugated with the anti-IGF1R antibody (AVE-1642) to detect and quantify IGF1R levels in breast cancer cells." (PMID 38730959, 2024). "Unlike with ITGB3, we observed a strong, positive correlation between IGF-1R and ITGB1 protein expression in basal-like breast cancer patients." (PMID 39608716, 2024). "Needle biopsy specimens at the time of breast cancer diagnosis were positive for somatostatin receptor 2 (SSTR2) and insulin-like growth factor 1 receptor (IGF-1R) immunostaining." (PMID 39238765, 2024). "Calycosin (100 μM) regulates the expression of ERβ, IGF‐1R, PI3K/Akt, and PARP‐1, inducing apoptosis and control of cell proliferation in multiple breast cancer cells." (PMID 38230908, 2024). "Overall, these data indicate that ITGB1 protein expression correlates with IGF-1R protein expression in breast cancer, particularly the basal-like subtype, and that high ITGB1 expression coincides with intracellular/Golgi-localized IGF-1R in migratory cells." (PMID 39608716, 2024). "IGFBPs sequester IGFs to attenuate binding to Insulin-like growth factor 1 receptor (IGF1R) which promotes proliferation and survival in breast cancer cells." (PMID 39698031, 2024). "For instance, TRAF4 has been reported to mediate IRS1 ubiquitination, regulating IRS1 binding with IGF-1R and subsequent IRS1 phosphorylation, leading to the stimulation of proliferation in breast cancer cells." (PMID 38272982, 2024). "Dysregulation of type 1 insulin-like growth factor receptor (IGF-1R) signaling activates PI3K and Ras/ERK signaling pathways and leads to increased breast cancer cell growth, proliferation, and survival." (PMID 39362991, 2024).
breast cancer (continued). "First, this is the first report of TSH-PitNET combined with breast cancer; second, the breast cancer specimen was positive for SSTR2 and IGF-1R immunoreactivity; third, the breast cancer showed a complete response after treatment with SSA and chemotherapy." (PMID 39238765, 2024). "The gene enrichment analysis, functional enrichment, and pathway analysis showed that EGFR and IGF1R are genes at the initial phase of the TNBC-specific pathway, and ERBB2 and 1ESR are involved in the hormone-dependent breast cancer pathway." (PMID 37629702, 2023). "They developed a bispecific sCAR-T cell to target two antigens on HER2+ breast cancer cells: HER2 and IGF1R." (PMID 37046648, 2023). "Others have shown that CR inhibits prostate cancer and breast cancer progression partially through the regulation of the IGF1/IGF1R axis." (PMID 37686596, 2023). "FOXO3a accelerated the trastuzumab resistance of HER2-positive breast cancer through targeting and up-regulating IGF2/IGF-1R/IRS1 signaling." (PMID 37529418, 2023). "Furthermore, in a subtype analysis of basal-like breast cancer, which includes a majority of TNBCs, we found that neither IGF1R nor IR were associated with a worse outcome (overall survival, relapse free survival or distant disease free survival) using in-silico analysis." (PMID 36920947, 2023). "Trastuzumab resistance in HER2-positive breast cancer involves increased EGFR and IGF1R signals as well as dysregulation of the PTEN/PI3K/AKT/mTOR pathway." (PMID 38114573, 2023). "In ERα-negative breast cancer, adiponectin inhibited IGF-1-induced cell migration, whereas in ERα-positive breast cancer, low concentrations of adiponectin promoted IGF-1R phosphorylation and thus enhanced IGF-1/IGF-1R signaling." (PMID 36755926, 2023). "In ER positive breast cancer, linsitinib abrogated increased phosphorylation of PI3K/MAPK proteins and Erα proteins as a result of the IGF-1R stimulation." (PMID 36920947, 2023). "In summary, the present study demonstrates that GASP1 is highly expressed in breast cancers, and plays an oncogenic role in breast cancer cells by forming a positive feedback loop with IGF1/IGF1R pathway." (PMID 36042202, 2022). "furthermore, the IGF-1Rβ levels are increased in breast cancer metastasis and disruption of IGF-1/IGF-1R signaling inhibited tumorigenesis in preclinical models." (PMID 35372035, 2022). "We found PRCP increased IGF1R/HER3 signaling and AKT activation in ER+ breast cancer cells that was blocked by PRCPi." (PMID 36332175, 2022). "The cell-surface IGF1 receptor (IGF1R), which mediates the biological actions of both IGF1 and IGF2, is regarded as a central player in breast cancer." (PMID 35432218, 2022). "In breast cancer, in model autoimmune diseases, as in TED, the binding of IGF-1 to IGF-1R triggers the PI3K/AKT/mTOR signaling pathway." (PMID 35784325, 2022). "SPCA1 knockdown induces the significant accumulation of inactive pro-form of IGF1R at the TGN and reduces the production of functional IGF1Rβ at the plasma membrane, thus resulting in the inhibition of breast cancer cell proliferation." (PMID 35805075, 2022). "Indeed, the IGF1/IGF1R system stimulates the FAK signal transduction pathway activation, which, in turn, regulates the nuclear accumulation of YAP (yes-associated protein/yes-related protein) and the expression of its target genes, thus inducing breast cancer cell proliferation." (PMID 35805075, 2022). "Antineoplastics targeting the IGF-1R and its ligands have largely disappointed in the clinic, despite extensive evidence that IGF signaling promotes many aspects of breast cancer progression." (PMID 36556357, 2022). "Overexpression of PRCP increased IGF1R/HER3 signaling and AKT-mTORC1 activation in ER+ breast cancer cells." (PMID 36332175, 2022). "Of particular relevance is the stimulation of the IGF1 receptor (IGF1R) which was found to form a heterotrimeric complex with HER2 and HER3 resulting in SRC activation in breast cancer cells." (PMID 36466034, 2022).